CXCR1 (C-X-C motif chemokine receptor 1)
Diseases named in the same sentence as CXCR1 in open-access papers (continued):
Sharing a sentence is not in itself a finding about the gene and the disease.
neuroblastoma (3 papers, 2021 to 2025). Neuroblastoma (NB) is the most common solid, extracranial childhood tumor. "In neuroblastoma cell lines, CXCR1 was up-regulated in SH-SY5Y, SK-N-MC, and SK-N-SH lines, whereas only SH-SY5Y and SK-N-MC lines displayed a positive correlation between the MYT1L protein and CXCR1 mRNA levels." (PMID 40362634, 2025). "Furthermore, CXCR5/CXCL13 and CXCR1/CXCL1 interactions may specifically contribute to neuroblastoma bone marrow metastasis in part by facilitating transmigration of neuroblastoma cells through the bone marrow endothelium." (PMID 34831167, 2021).
neutropenia (3 papers, 2022 to 2025). A decrease in the number of neutrophils found in the blood. "Chemotherapy, for example, can cause life-threatening neutropenia as a side effect, and blocking neutrophil migration via CXCR1 and CXCR2, and inhibiting G-CSF, inhibit neutrophil function." (PMID 35205709, 2022). "Even if CXCR1/2 inhibition therapies are really promising for treating various disorders, it would be crucial for future clinical applications to evaluate the possible unwanted side effects, such as neutropenia, increased risk infections and gastrointestinal problems." (PMID 39627194, 2024). "Unexpectedly, the proportions of circulating patient neutrophils at baseline expressing CXCR1 and CXCR2 were reduced in patients, which may reflect distorted distribution dynamics, and might also contribute to neutropenia-dependent immunodeficiency." (PMID 40330596, 2025).
osteoarthritis (3 papers, 2015 to 2021). A noninflammatory degenerative joint disease occurring chiefly in older persons, characterized by degeneration of the articular cartilage, hypertrophy of bone at the margins and changes in the synovial membrane. "We suggest that disruption of CXCR1/2 signalling is an important event in osteoarthritis, resulting in the loss of chondrocyte phenotypic stability and promoting OA-like changes." (PMID 25135253, 2015). "CXCR1/CXCR2 play a significant role in regulating tissue inflammation in a mouse model of osteoarthritis." (PMID 31139654, 2019). "The statistical results showed that the expression levels of ADIPOQ, IL6, and CXCR1 in the synovium of osteoarthritis were significantly increased (p <0.05)." (PMID 31139654, 2019). "The qRT-PCR results showed that the expression levels of ADIPOQ, IL6, and CXCR1 in the synovium of osteoarthritis were significantly increased (p <0.05)." (PMID 31139654, 2019). "Our study demonstrates an important physiological role for CXCR1/2 signalling in maintaining cartilage homeostasis and suggests that the loss of ELR+ CXC chemokines during cartilage breakdown in osteoarthritis contributes to the characteristic loss of chondrocyte phenotypic stability." (PMID 25135253, 2015). "Furthermore, although CXCR1 and CXCR2 are members of a family of chemokine receptors, they seem to play opposite roles in osteoarthritis." (PMID 34488536, 2021). "If CXCR1/2 signalling supports SOX9 expression, why did we not observe spontaneous osteoarthritis in CXCR2-deficient mice?" (PMID 25135253, 2015).
pancreatic ductal adenocarcinoma (3 papers, 2020 to 2022). An infiltrating adenocarcinoma that arises from the epithelial cells of the pancreas. "Reparixin, a CXCR1/2 inhibitor, had previously been used in a mouse model of pancreatic ductal adenocarcinoma to disrupt tumor/fibroblast interactions and improve overall survival in mice." (PMID 31504643, 2020). "Prompted by these promising results obtained in preclinical models, phase I and II clinical trials are evaluating the targeting of CXCR1 and CXCR2 in combination with anti-PD-1 in patients with metastatic melanoma, pancreatic ductal carcinoma, and Ras-mutated MSS metastatic colon carcinoma." (PMID 35158948, 2022). "For instance, a phase I study is probing a combination of SX-682 (a CXCR1/2 inhibitor) and nivolumab (anti-PD1) in metastatic pancreatic ductal adenocarcinoma (NCT04477343)." (PMID 36147630, 2022). "Inhibition of CXCR1 and/or CXCR2 by pharmacological or genetic approaches showed that limiting neutrophil infiltration resulted in reduced tumor growth in murine models of pancreatic ductal adenocarcinoma, colorectal cancer, lung adenocarcinoma, and rhabdomyosarcoma." (PMID 35158948, 2022).
Parkinson disease (3 papers, 2016 to 2022). A progressive degenerative disorder of the central nervous system characterized by loss of dopamine producing neurons in the substantia nigra and the presence of Lewy bodies in the substantia nigra and locus coeruleus. "In addition, several CD20- and CD33-expressing leukocytes increased the risk of Alzheimer’s disease; CD11-expressing leukocytes increased, and CD27- and CXCR1-expressing leukocytes decreased, Parkinson’s disease risk in MR sensitivity analyses." (PMID 37118290, 2022). "As an additional supportive finding, our MR sensitivity analyses showed that several CD20- and CD33-expressing leukocytes increase the risk of Alzheimer’s disease and that CD11-expressing leukocytes may increase, and CD27- and CXCR1-expressing leukocytes may decrease, Parkinson’s disease risk." (PMID 37118290, 2022).
periodontitis (3 papers, 2011 to 2024). An acute or chronic inflammatory process that affects the tissues that surround and support the teeth. "In this regard, the aim of this study was to investigate the association of the rs2234671 SNP in the CXCR1 gene in a Brazilian population with chronic periodontitis." (PMID 22051099, 2011). "The analysis revealed simultaneous significant upregulation of IL1β, SRGN, CXCR1, FGR, ARHGEF2, and PTAFR in all six periodontitis-related datasets." (PMID 38491529, 2024). "An online differential expression analysis conducted using OralExplorer revealed several genes that were significantly upregulated in all six periodontitis-related datasets, including IL-1β, SRGN, CXCR1, FGR, ARHGEF2, and PTAFR." (PMID 38491529, 2024). "Similar to the mRNA expression results, enhanced protein expression of IL1β, SRGN, CXCR1, and PTAFR was observed in the periodontitis group." (PMID 38491529, 2024). "Specifically, we observed that IL-1β, SRGN, CXCR1, and PTAFR exhibited significant upregulation at both the RNA transcript and protein translation levels in periodontitis patients compared to healthy periodontal patients." (PMID 38491529, 2024). "Additionally, we conducted immunohistochemical analysis to explore the protein translation of IL1β, SRGN, CXCR1, and PTAFR in patients with periodontitis." (PMID 38491529, 2024).
Stroke (3 papers, 2018 to 2025). Sudden impairment of blood flow to a part of the brain due to occlusion or rupture of an artery to the brain. "Our results suggest that modulating CXCR1 activity offers a novel therapeutic strategy for stroke." (PMID 29323156, 2018). "CXCR1 expression on microglia was not significantly altered by coculture with T cells from controls or stroke patients." (PMID 41373643, 2025). "Several chemokine receptors (eg CXCR1, CXCR2, CXCR3) are expressed in oligodendrocytes and show increased expression in MS, stroke and amyotrophic lateral sclerosis, and have been implicated in disorders in which myelin damage is associated with immune activation in the CNS." (PMID 29588250, 2018).
acute appendicitis (2 papers, 2016 to 2020). "There are several documents about upregulation of IL-8 and its receptor (CXCR1) within the mucosa of the inflamed appendix and blood in the patients with AA compared to the patients without appendicitis." (PMID 33585011, 2020). "Interestingly, 3 of the 37 DEG (LILRA3, CXCR1/IL8RA, FCGR3A), which were higher in appendicitis patients compared to abdominal pain patients, are near or exact matches to transcripts discovered previously as down-regulated by exposure of isolated human neutrophils to E. Coli." (PMID 27417541, 2016).
acute cystitis (2 papers, 2009 to 2010). An acute infection of the bladder. "Compared to controls and acute cystitis and urethritis patients, the genotype of CXCR1 (2608) GC in chronic UTI patients were also lower than the two groups (p = 0.003; 0.016)." (PMID 21151974, 2010). "Compared to acute cystitis and urethritis patients, chronic UTI patients also had lower CXCR1 (2608)C allele prevalence (p = 0.003)." (PMID 21151974, 2010). "The results of this study show that the prevalence frequencies of CXCR1 (2608) GC and CXCR1 (2608) C in UTI patients and patients with chronic UTI are lower than those in the healthy and acute cystitis groups, but expression levels of CXCR1 in neutrophils were not different." (PMID 21151974, 2010).
acute myeloid leukemia (2 papers, 2021 to 2023). Acute myeloid leukemia (AML) is a group of neoplasms arising from precursor cells committed to the myeloid cell-line differentiation. "Thus, we have examined the serum levels of these chemokines in parallel with their related cognate receptors (CXCR1, CXCR3 and CXCR4) in AML (acute myeloid leukemia) patients prior and post BMT (bone marrow transplantation) therapy." (PMID 34711015, 2021).
acute myocardial infarction (2 papers, 2020 to 2022). Necrosis of the myocardium, as a result of interruption of the blood supply to the area. "In conclusion, the combination of transcriptome analysis and subsequent RT-PCR, WB and IHC verification revealed that GXNI has a significant therapeutic effect on acute myocardial infarction in mice mainly via inhibiting the CXCR1-NF-κB-COX-2/ICAM-1/VCAM-1 pathway." (PMID 36325326, 2022). "Since GXNI treatment of acute myocardial infarction is mainly related to the anti-inflammatory effects mediated by CXCR1-NF-κB-COX-2/ICAM-1/VCAM-1-mediated IL-8 signaling pathway, the release of inflammatory factors and leukocyte infiltration were further examined." (PMID 36325326, 2022).
alcoholic liver diseases (2 papers, 2017). A disorder caused by damage to the liver parenchyma due to alcohol consumption. "CXCR1/2-specific pepducins not only protected mice from liver inflammation, weight loss and mortality associated with experimental alcoholic liver disease, but therapeutic administration cured disease and prevented further mortality in fully established disease." (PMID 26858343, 2017). "Here, we show that experimental alcoholic liver disease is driven by CXCR1/2-dependent activation of neutrophils." (PMID 26858343, 2017). "Moreover, recent study also showed that blocking of CXCR1/2 receptors with pepducins increases survival of a murine model of alcoholic liver disease, reverts liver inflammation and steatosis." (PMID 28484461, 2017).
atherosclerosis (2 papers, 2012 to 2026). A disease characterized by the build-up of fatty material and calcium deposition in the arterial wall resulting in partial or complete occlusion of the arterial lumen. "In the case of native atherosclerosis, recruitment of inflammatory Ly-6Chi monocytes into the atherosclerotic plaques requires particular chemokine–chemokine receptor interactions, involving CXCR1 in addition to CCR2 and CCR5." (PMID 22704806, 2012).
bronchiectasis (2 papers, 2011 to 2022). Segmental, irreversible dilation of the bronchial tree resulting in the accumulation of secretions which leads to obstruction. "Interestingly, airway neutrophils from healthy individuals express higher CXCR1 than blood neutrophils, whereas patients with sarcoidosis exhibit lower CXCR1 expression, similar to the PCD and bronchiectasis patients in our cohort." (PMID 36528664, 2022). "We detected reduced levels of the chemokine receptors CXCR1 and CXCR2 and an increased expression of the chemokine receptor CXCR4 on sputum neutrophils as compared to peripheral blood neutrophils, both in PCD and in bronchiectasis." (PMID 36528664, 2022).
chronic hepatitis B (2 papers, 2016 to 2017). "To demonstrate the role of CXCR1/CXCR2-expressing neutrophils in hepatic injury, we investigated CXCR1/CXCR2 receptor expression in 17 hepatitis B virus-related ACLF patients in comparison to 42 chronic hepatitis B and 18 healthy controls." (PMID 28484461, 2017).
Depression (2 papers, 2025 to 2026). "Notably, lower expression levels of MMP9 and CXCR1 were significantly correlated with higher Hamilton Depression Rating Scale (HAMD) scores, indicating greater symptom severity." (PMID 41696471, 2026).
diabetic kidney disease (2 papers, 2025). Progressive kidney disorder caused by vascular damage to the glomerular capillaries, in patients with diabetes mellitus. "Interestingly, preclinical data suggest that the use of Ladarixin, a non-competitive, dual allosteric inhibitor of CXCL8 (IL-8) receptors (CXCR1 and CXCR2), may reduce the burden of diabetic kidney disease as the IL-8-CXCR1/2 axis contributes to diabetic kidney disease." (PMID 40215252, 2025).
endometriosis (2 papers, 2007 to 2025). The growth of functional endometrial tissue in anatomic sites outside the uterine body. "CXCL8 played a crucial role by binding to CXCR1 and activating the PTEN/AKT pathway, thereby promoting proliferation and inhibiting apoptosis in endometriosis cells." (PMID 40757199, 2025). "Furthermore, glandular epithelial cell localisation and upregulation of immunoreactive CXCR1 and CXCR2, which bind CXCL8, has been demonstrated in eutopic and ectopic tissue sections from endometriosis patients when compared to controls." (PMID 17506907, 2007).
endometritis (2 papers, 2023 to 2024). An acute or chronic, usually bacterial infectious process affecting the endometrium. "For example, endometritis and CXCR1 SNPs have been linked in Holstein dairy cows." (PMID 37368756, 2023).
fibrosis (2 papers, 2011 to 2022). the formation of excess fibrous connective tissue in an organ or tissue in a reparative or reactive process. "The recent consideration of CXCR1/R2 allosteric inhibitors for therapy of inflammatory lung diseases associated with fibrosis suggests that these inhibitors might be effective in treating BM fibrosis." (PMID 35392239, 2022).
gout (2 papers, 2021 to 2026). A condition characterized by painful swelling of the joints, which is caused by deposition of urate crystals. "The study found that the CXCR1 gene rs2234671 and CXCR2 gene rs1126579 in the gouty arthritis group were not related to the susceptibility of gout in Chinese men." (PMID 35116032, 2021).
hepatitis B (2 papers, 2011 to 2021). "Genetic and expression variation in CXCR1 have been correlated with infections (e.g., active tuberculosis, hepatitis B, Candida albicans) and modestly with SLE." (PMID 34946847, 2021).
HIV-1 infection (2 papers, 2012 to 2014). The type species of lentivirus and the etiologic agent of acquired immunodeficiency syndrome (AIDS). "Overall, our study shows that CXCL8 enhances HIV-1 infection in macrophages and microglia through receptors CXCR1 and CXCR2 by downstream activation of NF-κB." (PMID 24662979, 2014). "Our findings compliment these studies and confirm the role of chemokine CXCL8 and receptors CXCR1/2 in regulating HIV-1 infection in MDM and microglia." (PMID 24662979, 2014). "CXCR1/2 inhibition in combination with ART might prove to be a better therapy for control of neuroinflammation in HIV-1 infection." (PMID 24662979, 2014).
injury (2 papers, 2014 to 2019). Damage inflicted on the body as the direct or indirect result of an external force, with or without disruption of structural continuity. "IL-8 binds to G protein–coupled chemokine receptors (CXCR) 1 and CXCR2, which promote neutrophil influx into tissue sites of inflammation and induce acute lung injury." (PMID 25501580, 2014).
ischemic stroke (2 papers, 2016 to 2023). A stroke disorder caused by obstruction of blood flow to the brain, due to thrombotic (local blood clot formation) or embolic (due to a blood clot or other material traveling from another site) event. "A recent paper reports CXCL5 (that binds with CXCR1 and CXCR2 and activates the p38 MAP kinase signaling pathways) to be upregulated in ischemic stroke." (PMID 36982232, 2023). "A blockade of CXCR1/2 chemokine receptors and ELR CXC chemokine antagonism protected mice in ischemic stroke." (PMID 27213359, 2016).
keloid (2 papers, 2018 to 2024). An irregularly shaped, elevated mark on the skin caused by deposits of excessive amounts of collagen during wound healing. "Our findings indicate that CXCR1 gene mutation and altered protein expression are associated with keloid scar development." (PMID 29931443, 2018). "Among the genes encoding mechanoreceptors, the expression of CXCR1 mRNA was significantly higher in keloid scar tissues than in the surrounding tissues of normal controls (P < 0.05)." (PMID 29931443, 2018). "We also found a novel heterozygous missense mutation c.574G > A(p.Gly192Glu) in the CXCR1 gene in a patient with keloid by Sanger sequencing." (PMID 29931443, 2018). "Identification of the CXCR1 gene mutation might provide insights into the molecular mechanism underlying keloid scar and underscores the potential importance of mechanoreceptors in keloid scar pathogenesis." (PMID 29931443, 2018). "Immunohistochemical staining confirmed an elevated expression of CXCR1 at the protein level in keloid as compared to controls." (PMID 29931443, 2018). "Immunohistochemical staining for CXCR1 was performed on keloids and surrounding normal controls that were biopsied from individuals with keloid." (PMID 29931443, 2018). "Immuno-histochemical staining (IHS) identified differential CXCR1 protein expression in keloid tissues compared with controls." (PMID 29931443, 2018). "Taken together, our findings suggest that CXCR1 probably participates in human keloid formation as a mechano-receptor." (PMID 29931443, 2018). "We found significantly elevated CXCR1 expression in keloid tissues as compared to healthy control skin tissues with high and low tension (P < 0.05)." (PMID 29931443, 2018). "Immunohistochemistry showed heightened protein expression of CXCR1 in keloid scars as compared to controls." (PMID 29931443, 2018). "We found elevated protein expression of CXCR1 in keloid tissues as compared to healthy controls not only in the high tension group but also in the low tension group." (PMID 29931443, 2018). "Moreover, the data show elevation of interleukin-8 (IL-8) in both the circulation and keloid tissue, which elicited the collagen accumulation and migratory program of dermal fibroblasts via CXCR1/2 receptor." (PMID 39081787, 2024). "However, no study has yet been conducted to determine the correlation between CXCR1 and keloid formation." (PMID 29931443, 2018).
leukaemia (2 papers, 2024). "Furthermore, HSC-prog cells showed more interactions with other cells through known ligand–receptor pairs, such as leukaemia-associated ligands CXCL2, CXCL3, and FLT3, signalling to the receptors CXCR1 and CXCR2 expressed by CD14-mono and NK cells." (PMID 37615858, 2024).
liver failure (2 papers, 2021 to 2022). A liver disease characterized by the liver losing or has lost all of its function. "The suppression of CXCR1/2 on neutrophils potentially protects the body from systemic inflammation favoring the development of liver failure." (PMID 36451225, 2022). "In addition, CXCR1/2 blockade restrains systemic inflammation in mice with peritonitis and liver failure." (PMID 36451225, 2022).
lung adenocarcinoma (2 papers, 2022 to 2023). A carcinoma that arises from the lung and is characterized by the presence of malignant glandular epithelial cells. "The LUAD tissues displayed low (3/3) CXCR1 staining and the CXCR1 staining in lung adenocarcinoma cells was usually not detected (11/11)." (PMID 35768814, 2022).
medulloblastoma (2 papers, 2015 to 2022). A malignant, invasive embryonal neoplasm arising from the cerebellum. "When hAT-MSCs were co-cultured with medulloblastoma-BTICs, the expression levels of CCR4, CCR5, CCR7, XCR1, CXCR1, CXCR4, PDGFR-bb, KDR and TEK were increased, while the levels of CX3CR1, IL1R, IL6R, IL8R, IGF1R and CD44 were decreased (p<0.05)." (PMID 26076490, 2015).